GTF2H2 (general transcription factor IIH subunit 2)
Description:
Component of the general transcription and DNA repair factor IIH (TFIIH) core complex, which is involved in general and transcription-coupled nucleotide excision repair (NER) of damaged DNA and, when complexed to CAK, in RNA transcription by RNA polymerase II. In NER, TFIIH acts by opening DNA around the lesion to allow the excision of the damaged oligonucleotide and its replacement by a new DNA fragment. In transcription, TFIIH has an essential role in transcription initiation. When the pre-initiation complex (PIC) has been established, TFIIH is required for promoter opening and promoter escape. Phosphorylation of the C-terminal tail (CTD) of the largest subunit of RNA polymerase II by the kinase module CAK controls the initiation of transcription. The N-terminus of GTF2H2 interacts with and regulates XPD whereas an intact C-terminus is required for a successful escape of RNAP II form the promoter.
Synonyms: BTF2 p44; BTF2P44; BTF2; TFIIH; T-BTF2P44; p44
Tractability: Small molecule: a structure with a bound ligand is known. PROTAC: ubiquitination databases record sites on it; its protein half-life has been measured.
Gene: Protein-coding gene on chromosome 5 (71,034,962 to 71,067,723, reverse strand). Ensembl gene ENSG00000145736.
Subcellular location: Nucleus
Subcellular location (Human Protein Atlas): Nuclear speckles
Pathways (Reactome):
Gene expression (Transcription): Formation of RNA Pol II elongation complex; Formation of the Early Elongation Complex; NoRC negatively regulates rRNA expression; RNA Pol II CTD phosphorylation and interaction with CE; RNA Polymerase I Promoter Escape; RNA Polymerase I Transcription Initiation; RNA Polymerase I Transcription Termination; RNA Polymerase II Pre-transcription Events; RNA Polymerase II Promoter Escape; RNA Polymerase II Transcription Elongation; RNA Polymerase II Transcription Initiation; RNA Polymerase II Transcription Initiation And Promoter Clearance; RNA Polymerase II Transcription Pre-Initiation And Promoter Opening
Disease: Formation of HIV elongation complex in the absence of HIV Tat; Formation of HIV-1 elongation complex containing HIV-1 Tat; Formation of the HIV-1 Early Elongation Complex; HIV Transcription Initiation; RNA Pol II CTD phosphorylation and interaction with CE during HIV infection; RNA Polymerase II HIV Promoter Escape; Tat-mediated elongation of the HIV-1 transcript; Transcription of the HIV genome
DNA Repair: Dual Incision in GG-NER; Dual incision in TC-NER; Formation of Incision Complex in GG-NER; Formation of TC-NER Pre-Incision Complex; Gap-filling DNA repair synthesis and ligation in TC-NER; Transcription-Coupled Nucleotide Excision Repair (TC-NER)
Metabolism of RNA: mRNA Capping
Gene Ontology:
Molecular function: protein binding; RNA polymerase II general transcription initiation factor activity; zinc ion binding
Biological process: G protein-coupled receptor internalization; transcription by RNA polymerase II; transcription initiation at RNA polymerase II promoter; nucleotide-excision repair; response to UV; DNA repair; DNA-templated transcription
Cellular component: core TFIIH complex portion of holo TFIIH complex; nuclear speck; nucleus; transcription factor TFIID complex; transcription factor TFIIH core complex; transcription factor TFIIH holo complex; nucleoplasm
Genetic constraint (gnomAD): Loss-of-function variants: 1 observed, 1.42 expected, observed/expected ratio (o/e) 0.71, 90% interval 0.22 to 1.85. That is too few expected variants to judge how well the gene tolerates losing a copy. Missense variants: 12 observed, 25.76 expected, observed/expected ratio (o/e) 0.47, 90% interval 0.3 to 0.75. Synonymous variants: 2 observed, 6.83 expected, observed/expected ratio (o/e) 0.29, 90% interval 0.12 to 0.92.
Homologues: Orthologues: mouse Gtf2h2 (97% identical), rat Gtf2h2 (97% identical), macaque GTF2H2 (88% identical), tropical clawed frog gtf2h2 (84% identical), zebrafish gtf2h2 (81% identical), Drosophila melanogaster Ssl1 (52% identical), Caenorhabditis elegans gtf-2H2C (41% identical). Paralogues in human: GTF2H2C (99% identical).
Diseases named in the same sentence as GTF2H2 in open-access papers:
GTF2H2 is named in the same sentence as 12 diseases in open-access papers, as found by Europe PMC text mining. Sharing a sentence is not in itself a finding about the gene and the disease. The quoted sentences say what the papers report.
spinal muscular atrophy (4 papers, 2018 to 2022). A motor neuron disease that affect the muscles, and characterized by muscle weakness and atrophy resulting from progressive degeneration and irreversible loss of the anterior horn cells in the spinal cord (i.e., lower motor neurons) and the brain stem nuclei. "GTF2H2 has been linked in human to spinal muscular atrophy and to the neurodegenerative disorder Cockayne syndrome." (PMID 36672761, 2022). "GTF2H2 has been previously implicated as a modifier gene in spinal muscular atrophy (SMA), an autosomal recessive neurodegenerative disorder characterized by progressive death of motor neurons, implying proximal muscle weakness, and wasting in the absence of sensory signs." (PMID 31998221, 2019). "The study evidenced a new variant associated with PD (rs201330591) in the GTF2H2 gene, previously implicated in spinal muscular atrophy (SMA), which was not replicated in other independent European cohorts." (PMID 32640513, 2020).
breast carcinoma (3 papers, 2011 to 2022). "Eight of these 29 (28%) CNV loci were confirmed by qPCR and/or Nanostring analysis, including four loci that were associated with breast cancer (GTF2H2, ZNF385B, NAALADL2 and PSG5) and two loci that were associated with ovarian cancer (CYP2A7 and OR2A1)." (PMID 28145423, 2017). "These include four loci that were associated (unadjusted P<0.05) with breast cancer (GTF2H2, ZNF385B, NAALADL2 and PSG5), and two loci associated with ovarian cancer (CYP2A7 and OR2A1)." (PMID 28145423, 2017). "Deletions overlapping GTF2H2 are associated with decreased risk of breast cancer, suggesting that disruption of NER may be protective against the biological consequences of a BRCA1 pathogenic variant." (PMID 28145423, 2017). "GTF2H2 was reported to be associated with chemoresistance in non-small cell lung cancer and breast cancer." (PMID 35615147, 2022). "GTF2H2 (5q13.2) is a transcription factor with a role in the nucleotide excision repair (NER) pathway, a DNA repair pathway that is disrupted in BRCA1-associated breast cancers." (PMID 28145423, 2017).
mesothelioma (1 paper, 2014). A usually malignant and aggressive neoplasm of the mesothelium which is often associated with exposure to asbestos. "There are also several similarities with mesothelioma in this respect where overexpression of two or more of CDK7, GTF2H2, PCNA, RFC4, and the RFC5 were shared by the lung tumors." (PMID 25325012, 2014).
myasthenia (1 paper, 2016). "This patient was first hospitalized due to pneumonia and myasthenia when he was 1 month old in May 2013, who was homozygous for the SMN exon 7 deletion, and the remaining 1999 samples were negative for SMN, NAIP and GTF2H2 deletion." (PMID 27534852, 2016).
pneumonia (1 paper, 2016). An acute, acute and chronic, or chronic inflammation focally or diffusely affecting the lung parenchyma, caused by an infection in one or both of the lungs (by bacteria, viruses, fungi, or mycoplasma.). "There was a much lower survival rate in patients with a homozygous deletion in NAIP or GTF2H2 (p < 0.01), particularly in the first 2 months after suffering from pneumonia." (PMID 27534852, 2016).
tumor (4 papers, 2022 to 2024). "We thus examined the roles of the N-terminal region of E2F1 in the regulation of tumor suppressor genes in relation to GTF2H2." (PMID 39595534, 2024). "Taken together, these results suggest that the N-terminal region of E2F1 contains a novel transactivation domain that mediates the activation of tumor suppressor genes, at least in part, by recruiting GTF2H2." (PMID 39595534, 2024). "ARID1A tended to have a positive correlation with tumor size and tumor stage while GTF2H2 and PRKRIR tended to have a negative correlation with tumor size and tumor stage." (PMID 35615147, 2022).
cancer (2 papers, 2022 to 2024). A tumor composed of atypical neoplastic, often pleomorphic cells that invade other tissues. "Our results point to the crucial roles of GTF2H2 in the activation of tumor suppressor genes by deregulated E2F1, thereby providing a potential new target in cancer treatment." (PMID 39595534, 2024).
GTF2H2 also shares sentences with these, for which no sentence is quoted: lung carcinoma (2 papers); Cockayne syndrome (1); infection (1); non-small cell lung carcinoma (1); ovarian carcinoma (1).